Y_RNA (Y RNA )
Gene: Miscellaneous RNA gene on chromosome 14 (73,858,061 to 73,858,165, reverse strand). Ensembl gene ENSG00000223300.
Homologues: Orthologues: chimpanzee Y_RNA (96% identical). Paralogues in human: Y_RNA (81% identical), RNY1P16 (78% identical), Y_RNA (78% identical), Y_RNA (77% identical), RNY1 (76% identical), RNY1P5 (76% identical), Y_RNA (76% identical), RNY1P11 (75% identical), Y_RNA (75% identical), Y_RNA (74% identical), RNY1P13 (73% identical), Y_RNA (73% identical), and 92 more.